INS (insulin)
Diseases named in the same sentence as INS in open-access papers (continued):
Sharing a sentence is not in itself a finding about the gene and the disease.
breast cancer (continued). "Insulin use (mainly human insulin) for ≥3 years may be associated with a higher risk of breast cancer mortality." (PMID 26171401, 2015). "The findings of this large population-based study suggested that prolonged exposure to human insulin may increase the risk of breast cancer after multivariable adjustment." (PMID 26537234, 2015). "Additional analyses suggested that the breast cancer risk associated with human insulin use might be beneficially modified by concomitant use of metformin, statin and ACEI/ARB." (PMID 26537234, 2015). "This could provide a suggestion that treatment with human insulin analogues may initiate the development of mammary tumors with an altered mutational and/or signaling spectrum." (PMID 25848982, 2015). "The findings suggest that insulin use might be associated with a higher risk of breast cancer mortality if the duration of its use is ≥3 years." (PMID 26171401, 2015). "Because mortality and incidence are different clinical entities and may be linked to different factors, whether insulin use is a risk factor for breast cancer incidence awaits further investigation." (PMID 26171401, 2015). "The higher risk of breast cancer mortality seen in the patients with exposure to exogenous insulin for ≥3 or ≥5 years indicates an appropriate period for incubation, which should eliminate the concern of biological plausibility associated with a short duration of exposure." (PMID 26171401, 2015). "Furthermore, studies variably included incident and prevalent users of insulin compromising estimates of association between the duration of use and breast cancer development." (PMID 26242987, 2015). "However, animal data were limited and there is not a single very well-designed epidemiological study to have investigated insulin treatment and breast cancer risk as the main outcome, and with sufficient power." (PMID 26242987, 2015). "Collectively, these observations lead to the hypothesis that breast cancer risk may be increased in women with elevated plasma insulin levels." (PMID 24911052, 2014). "For example, elevated insulin levels have been implicated in in vivo mouse models of breast cancer." (PMID 25373319, 2014). "Since a possible way for carbohydrates to be linked to breast cancer risk is through their effect on insulin levels, several lines of evidence suggest that insulin levels may directly or indirectly affect breast cancer risk." (PMID 25525466, 2014). "A high estrogen level is suspected to increase breast cancer risk, and other hormones such as progesterone, androgen derived from the ovaries and adrenal, thyroid hormones and insulin may play important roles in breast cancer development." (PMID 25926863, 2014). "Indeed, high levels of circulating insulin have been associated with increased risk of breast cancer in post-menopausal women." (PMID 25373319, 2014). "In addition to the endocrine effect of insulin, paracrine effect of insulin on secretion of adipokines has also been demonstrated to influence breast cancer risk and progression." (PMID 23826297, 2013). "Women with low BMI or WHR, particularly those with menopausal symptoms, are likely to have lower estrogen or insulin levels, which could translate into lower risk for breast cancer recurrence and better prognosis." (PMID 24098745, 2013). "Effect of oral diabetics and insulin therapy on breast cancer risk was also evaluated." (PMID 23401790, 2013). "Insulin may mediate breast cancer risk via both direct and indirect effects, resulting in increased concentration of androgens and estrogens, along with increased concentration of IGF-I." (PMID 22295251, 2012). "For example, elevated plasma insulin levels are associated with a higher risk of hepatocellular carcinoma in carriers of hepatitis B virus, whereas higher C-peptide levels are associated with increased mortality from breast cancer." (PMID 23209929, 2012).
breast cancer (continued). "Phospholipases (PLCs) are tyrosine kinase substrates that provide diacylglycerols (DAGs) for intracellular signaling in various contexts and its isoform PLCγ is known to be implicated in intracellular insulin signaling and in colon and breast cancer progression." (PMID 22554284, 2012). "Insulin is implicated as a link between obesity and breast cancer risk." (PMID 22295251, 2012). "Evidence for this CSC-centered hypothesis underlying breast cancer prevention by metformin is the observation of increased breast cancer risk within 2 years in diabetic women receiving the insulin analog glargine." (PMID 22203527, 2011). "Furthermore, insulin stimulates the ovaries to produce androgens, which have been linked to increased breast cancer risk." (PMID 20148110, 2010). "Cohort studies have found that women surgically treated for breast cancer with high fasted insulin levels had substantially increased risk for reoccurrence and death and that the highest tertile of fasted insulin levels was associated with a 2-fold increase in post-menopausal breast cancer risk." (PMID 20148110, 2010). "In colorectal cancer patients, higher dietary insulin scores after colorectal cancer diagnosis were associated with a statistically significant increase in colorectal cancer-specific and overall mortality, indicating poorer survival, and reduced mortality after breast cancer diagnosis." (PMID 40005424, 2025). "Although artificial sweeteners are not directly associated with genetic mutations, they may indirectly interfere with estrogen balance and increase breast cancer risk by affecting metabolic function and insulin sensitivity, especially when consumed over a long period of time." (PMID 39767777, 2024). "Some studies have pointed out that artificial sweeteners may increase the risk of breast cancer through mechanisms such as hormone disorders, changes in insulin response, and changes in intestinal microbiota, but these hypotheses still need further clinical verification." (PMID 39767777, 2024). "Additionally, the use of the 2 × 2 factorial design to examine relative effects of exercise and weight loss, or their combination on biomarkers of breast cancer recurrence (insulin, C-peptide, glucose, and clinically relevant indices such as HOMA2-IR and HOMA2-β) was novel." (PMID 34578984, 2021). "Some of these effects include insulin tolerance through the disruption of beta-pancreatic cells’ physiologic activity, disruption of physiologic prostate development or increased risk for prostate cancer in men and breast cancer in women or alterations in the physiology of mammary gland development." (PMID 32295303, 2020). "Several observational epidemiological studies have demonstrated that high levels of endogenous insulin are associated with higher risk of cancer incidence and mortality, including risk of colorectal, endometrial, prostate and breast cancer and breast cancer mortality." (PMID 32705315, 2020). "Our study suggests that the presence of the minor C allele of rs11212617 might associate with a significant improvement in insulin sensitivity in HER2-positive breast cancer patients subjected to neoadjuvant metformin in combination with trastuzumab and chemotherapy." (PMID 30984619, 2019). "Therefore, insulin and glycemic control could be a potential pathway through which whole grains may reduce breast cancer risk." (PMID 30241536, 2018). "Moreover, the association between abdominal fat and breast cancer in premenopausal women may be more related to higher production of insulin, insulin growth factor 1, and adipokines than to estrogen." (PMID 30112392, 2018). "Because our previous studies suggested that use of insulin and/or sulfonylurea are associated with a significantly higher risk of breast cancer, the higher proportions of their use in ever users of rosiglitazone might have only underestimated the beneficial effect of rosiglitazone." (PMID 27936468, 2017).
breast cancer (continued). "Given the retrospective nature of these studies and the possibility that the comparison treatments (such as sulfonylureas or exogenous insulin) may increase risk, randomized, placebo-controlled intervention trials are needed to assess the breast cancer preventive activity of metformin." (PMID 27430256, 2016). "Therefore, indication bias may exist when insulin is used in patients having more comorbidities and using more concomitant drugs that may also affect the risk of breast cancer." (PMID 26537234, 2015). "Insulin per se may be able to increase the risk of breast cancer through several mechanisms." (PMID 26537234, 2015). "Therefore, it is clinically important to clarify whether human insulin can be associated with breast cancer." (PMID 26537234, 2015). "We believe that measuring insulin levels in the 3-hour period after a sugar load test can provide better information and potentially peak levels of insulin or the area below the 3-hour insulin curve may be associated with breast cancer risk." (PMID 24911052, 2014). "A high BMI is associated with higher production of oestrogen in adipose tissues, altered mammary stromal environment and higher insulin levels, and it has been suggested that these factors may mediate the positive association of BMI with breast cancer risk in postmenopausal women." (PMID 21811252, 2011). "Breast cancer has been suggested to be associated with the insulin resistance syndrome; a fibre-rich diet could slow digestion and absorption of carbohydrates and influence plasma insulin response." (PMID 14710218, 2004). "There was a marginally higher frequency of breast cancer among insulin users [RR 0.98; 95% CI (0.90–1.06)]." (PMID 40572709, 2025). "Our findings suggest the profound impact of metabolic health, particularly insulin sensitivity, on the prognosis of breast cancer survivors." (PMID 41310487, 2025). "The involvement of insulin signaling in tumorigenesis has raised the possibilities for adopting therapeutic strategies to target insulin signaling in breast cancer patients." (PMID 40374694, 2025). "Insulin stimulates the proliferation of certain human breast cancer cell lines in vitro through the phosphatidylinositol-3 kinase and mitogen-activated protein kinase (MAPK)/Akt signaling pathways." (PMID 39857438, 2025). "Insulin signaling has been shown to stimulate breast cancer cell proliferation and survival, highlighting the importance of metabolic health in managing breast cancer risk." (PMID 39857438, 2025). "Lower levels of insulin and IGF-1 reduce cellularproliferation and mutation risk, while decreased estrogen exposureis particularly protective against breast cancer development." (PMID 41183009, 2025). "Calip and associates, in 2016, evaluated metformin users, sulfonylureas users, and insulin users in a group of breast cancer patients." (PMID 40572709, 2025). "The presence of GLUT4 has been demonstrated in insulin-independent tissues, such as the mammary gland, and also in breast cancer cells, where it plays a role in cell cycle progression." (PMID 40003620, 2025). "There was a marginally higher frequency of breast cancer among patients consuming insulin [RR 0.98; 95% CI (0.90–1.06)]." (PMID 40572709, 2025). "Our preliminary studies have demonstrated that exosomes from IR adipocytes promote significant EMT and tumor progression in breast cancer models, compared to insulin-sensitive controls." (PMID 40629272, 2025). "At the molecular level, T2DM and breast cancer share common pathways involving insulin and insulin-like growth factor (IGF) signaling." (PMID 40764810, 2025). "We build on our previous reports demonstrating that plasma exosomes from obese, diabetic patients, and exosomes from insulin-resistant 3T3-L1 adipocytes, upregulate key transcriptional signatures of epithelial-mesenchymal transition in breast cancer." (PMID 40629272, 2025).
breast cancer (continued). "Demographic, anthropometric, metabolic parameters of glucose and insulin, and behavioral characteristics of all participants, non‐cancer participants, cancer survivors, and breast cancer survivors from NHANES 2011 to 12 and 2013 to 2014." (PMID 40937951, 2025). "Consistent with the trend of insulin change, patients in the breast cancer group had a persistent elevation in C-peptide." (PMID 38414619, 2024). "These conditions have been observed previously in our reports concerning insulin and adipocytokines in obese women with breast cancer." (PMID 38397883, 2024). "Hormonal disturbances, particularly involving estrogen and insulin pathways, play a crucial role in breast cancer development and progression." (PMID 39767777, 2024). "In a study of women undergoing mastectomy or breast cancer surgery, CLS was detected in 40% of cases, and was associated with higher levels of insulin, glucose, leptin, triglycerides, C-reactive protein and IL-6." (PMID 39251829, 2024). "We estimated risk ratios for sex-steroid hormone biomarkers in relation to postmenopausal estrogen receptor (ER)-positive breast cancer, while accounting for biomarkers from insulin/insulin-like growth factor-signaling and inflammatory pathways." (PMID 38363402, 2024). "Of note, two recent systematic reviews found insufficient evidence to establish a causal link between the inflammation and insulin/IGF-signaling pathways and breast cancer." (PMID 38363402, 2024). "PRS categories included breast cancer (108 scores), lipid (65 scores), insulin (23 scores), cardio (47 scores), and general health and disease (54 scores)." (PMID 39057719, 2024). "One study from the Women’s Health Initiative presented results for estradiol with and without adjustment for free IGF-1 and insulin; positive associations with postmenopausal breast cancer appeared stronger with adjustment for both IGF-1 and insulin." (PMID 38363402, 2024). "A study reported that compared with the lowest quartile, the highest quartile of insulin and HOMA-IR was associated with the greatest risk of breast cancer among 5,064 Chinese women." (PMID 38904041, 2024). "Elevated insulin and IGF levels have been associated with increased breast cancer risk, as these hormones can promote cell proliferation and inhibit apoptosis (programmed cell death)." (PMID 39767777, 2024). "Physical training had limited overall benefits on insulin concentrations after glucose administration in breast cancer survivors." (PMID 38339407, 2024). "Along those lines, studies employing radiation-induced BC models highlighted that parity and age of radiation exposure, and elevated insulin and leptin levels, leading to increased energy availability, promote mammary tumor development." (PMID 38913216, 2024). "Insulin increases aromatase synthesis in mammary adipose cells and ER expression in tumor cells, presumably supporting the development of estrogen-dependent breast cancer." (PMID 39329990, 2024). "Studies with both insulin analogues, blocking and stimulating anti-IR antibodies, and small molecule inhibitors, have shown a role for insulin signalling in breast cancer development and progression." (PMID 39251829, 2024). "Despite extensive data reported in the literature, in our study, none of the analyzed biomarkers in the inflammation pathways, insulin-IGF axis, or sex hormones played a role in mediating the effect of BMI on breast cancer risk." (PMID 38999846, 2024). "In the context of breast cancer, metformin hinders the proliferation of tumor cells by affecting mitochondrial metabolism via a decrease in insulin levels." (PMID 39337461, 2024). "In contrast, insulin promotes the proliferation of breast cancer cells while inhibiting the progression of the tumor by obstructing the mitochondrial complex I and PI3K pathways." (PMID 39337461, 2024).
breast cancer (continued). "These knockout mice also exhibited enhanced insulin sensitivity, decreased insulin secretion, reduced blood levels of inflammatory and angiogenic factors, and diminished incidence and growth of mammary tumors." (PMID 39334887, 2024). "The upregulated genes were mainly involved in the insulin signaling pathway, which is proven to be an important factor for breast cancer prognosis." (PMID 38791477, 2024). "Analyzing the role of insulin in breast cancer development, its complex interaction with estrogen was described." (PMID 39329990, 2024). "The review has also emphasized the involvement of other hormones, such as insulin and growth factors, and their cross-talk with hormone pathways in breast cancer progression." (PMID 37575755, 2023). "In breast cancer, Metformin reduces tumor cell proliferation by decreasing insulin level since insulin promotes breast cancer cell proliferation, meanwhile, it suppresses tumor progression via inhibiting complex I and PI3K pathway." (PMID 36778129, 2023). "In recent studies involving patients treated for breast cancer and rheumatoid arthritis, a reverse relationship has been observed between serum insulin, osteocalcin, and ESR23,24." (PMID 37330595, 2023). "The suppression of glycolysis and insulin granule exocytosis in pancreatic β-cells carries substantial consequences for breast cancer patients." (PMID 38707985, 2023). "The insulin/IGF1R signaling pathway is observed to be activated in 75% of breast cancers and 87% of invasive breast cancers, respectively." (PMID 37237509, 2023). "Previous studies have suggested an association between pharmaceutical agents and cancer, including insulin use and breast cancer, antihypertensives and skin cancer, and sitagliptin and pancreas cancer, but these associations have not yet been confirmed." (PMID 37933755, 2023). "A bi-directional relationship was observed between dysregulated glucose/insulin metabolisms with breast cancer." (PMID 37511200, 2023). "Numerous studies have shown the benefits of combined interventions of exercise plus diet on lipid profile, insulin, adiponectin, leptin and ghrelin in breast cancer patients." (PMID 36839371, 2023). "Cell proliferation has been linked to metabolic syndrome, characterized by increased BMI and circulating insulin and growth factors, suggesting their mutual involvement in breast cancer progression." (PMID 37373357, 2023). "Exercise has beneficial effects on fasting insulin levels, fatigue, body composition, and cardiovascular function in patients with breast cancer." (PMID 36864418, 2023). "Previous studies showed that injecting mice with insulin triggered mammary tumor formation, while in rats, tumor-like pathologies were observed in the colon." (PMID 37511575, 2023). "Extracellular vesicles secreted by breast cancer cells inhibit insulin secretion through miR-122, thereby damaging systemic glucose homeostasis and promoting tumor growth." (PMID 38179409, 2023). "An increase in breast density was reported after a mammography screening-based study design performed on age-matched T2DM breast cancer patients after long-term insulin exposure." (PMID 37510134, 2023). "In contrast, previous studies have shown that many types of cancer, such as colorectal, prostate, and breast cancer, were promoted by abnormal insulin production." (PMID 36830954, 2023). "Concentrations of C‐peptide—a marker for insulin secretion—were measured at inclusion prior to cancer diagnosis in serum from 610 incident postmenopausal breast cancer cases and 1130 matched controls." (PMID 37096432, 2023). "A protective effect of insulin was observed on breast cancer in the review, but the etiology is unclear." (PMID 37481610, 2023). "Extensive pre-clinical and clinical results support the crucial role of the insulin/IGF system on breast cancer development, chemoresistance, and progression." (PMID 37361518, 2023).